CXCL13 (C-X-C motif chemokine ligand 13)
Diseases named in the same sentence as CXCL13 in open-access papers (continued):
Sharing a sentence is not in itself a finding about the gene and the disease.
psoriasis (23 papers, 2016 to 2026). An autoimmune condition characterized by red, well-delineated plaques with silvery scales that are usually on the extensor surfaces and scalp. "The results demonstrated that CCL20, ADAMDEC1, and CXCL13 exhibited strong diagnostic performance in both BC and psoriasis." (PMID 38605947, 2024). "Our data adds to increasing evidence that CXCL13 represents a particularly Th17-specific abnormality and positively associates with psoriasis severity, nominating it as a clinically useful biomarker for cutaneous disease." (PMID 35958578, 2022). "Our study found that CXCL13 is related to the pathogenesis of psoriasis, confirming its significance in modulating inflammation and cell migration." (PMID 40557155, 2025). "In a support vector machine classifier comparing psoriasis and healthy transcriptomes, the CXCL13 showed comparable or superior accuracy to IL17A as an indicator of psoriasis severity." (PMID 41169094, 2025). "This is consistent with our findings and opens up opportunities to further explore CXCL13’s role in psoriasis pathophysiology." (PMID 40557155, 2025). "CXCL8 and CXCL13 have already been implicated in early disease stages, with CXCL8 upregulated in mild psoriasis and CXCL13 expressed by lesion-infiltrating T cells, correlating with IL-17A levels." (PMID 40943056, 2025). "The heatmaps revealed an increase in several classic proinflammatory cytokines such as Tnf, Il6, Il1a, Il23α and a small number of chemokines, including Ccl19, Ccl20, Cxcl13, and Cxcl5, which are typically elevated in psoriasis patients, in CD169+ macrophages." (PMID 38891893, 2024). "Plasma CXCL13 levels are positively correlated with the frequency of peripheral helper T 17 (Tph17) cells and Tfh cells in peripheral blood of psoriasis patients." (PMID 35309354, 2022). "CXCL13 circulating levels and CXCL13 expression levels in cutaneous lesions are increased in psoriasis, and are positively correlated with disease severity." (PMID 35309354, 2022). "Specifically, through supplementary validation of gene expression using the psoriasis dataset, the distinctively high expression characteristics of CXCL13 and GNLY in DLE were revealed, thereby corroborating their central status as characteristic markers of DLE." (PMID 41214060, 2025). "In addition, 84.7% of CD161+ T-cell cluster cells expressed CXCL13, while only 1.6% of CD8+ T-cell cluster cells, 2.5% of CD4+ T-cell cluster cells, and 0.6% of Treg cluster cells expressed CXCL13 in pretreatment psoriasis lesional skin." (PMID 37781383, 2023). "Additionally, subsets of CD8+ T cells, characterized by expression of IL-17 pathway cytokines, cytolytic genes, and CXCL13, were specifically detected in psoriasis lesions." (PMID 35309354, 2022). "Similarly, CXCL13 expression was reported to be positively correlated with the severity of psoriasis." (PMID 36389813, 2022). "In addition to the cytokines noted above such as IL17F (0.967), and CXCL13 (0.325), this set contained identified psoriasis-specific genes with less established functional roles, such as ARHGEF12 (0.303), ENTPD1 (0.628), LAYN (0.122) and HAVCR2 (0.560)." (PMID 35958578, 2022). "Besides, CXCL13, which achieved greater accuracy than IL-17A, was thought as a novel biomarker of psoriasis severity." (PMID 34777377, 2021). "To elucidate the primary cellular sources of CXCL13 in skin diseases, we conducted an in-depth analysis of the ImmuneSingleCell skin atlas, a comprehensive database encompassing 18 distinct skin disorders, including cSCC, basal cell carcinoma, keloid, and psoriasis." (PMID 40352278, 2025). "Some studies indicate that CD274 (PD-L1), CXCL13, BIRC5, and SMPD3 are important in the pathogenesis of psoriasis." (PMID 40557155, 2025). "We examined the expression of cytokines previously reported to be involved in psoriasis, and found that IL17A, IL26, and CXCL13 were specifically expressed by CD8+ TRM17 and Cycling CD8+ TRM17." (PMID 41162356, 2025).
psoriasis (continued). "The ROC curves demonstrated that the expression levels of eight Hub Genes—POSTN, CD274, CD24, SERPINB3, CXCL13, SMPD3, BIRC5, and RAB27A—exhibited high accuracy (AUC > 0.9) in classifying the Psoriasis and Control groups." (PMID 40557155, 2025). "CXCL13 was highly and almost specifically expressed in CTCL compared with healthy skin, AD and psoriasis, probably explaining the enrichment of B cells in CTCL." (PMID 39558094, 2024). "We examined the expression of cytokines previously reported to be involved in psoriasis, and found that IL17A, IL17F, IL26, CCL20, CXCL13, IL22, and IL23R were specifically expressed by Tc17 cells." (PMID 37308489, 2023). "According to our analysis, with the treatment of immunosuppressants in psoriasis, the expression of IL-37 increased gradually, while IL-19, CXCL1, CXCL2, CXCL13 decrease gradually." (PMID 36389813, 2022). "Transcriptome analysis showed that CXCL13 and CCL20 were activated in both BC and psoriasis." (PMID 38605947, 2024). "We discovered that CXCL13 and CCR20 activation was evident in both BC and psoriasis." (PMID 38605947, 2024). "In a mouse model of psoriasis-like skin inflammation induced by imiquimod (IMQ), L-theanine significantly reduced the inflammatory response and down-regulated the expression of keratin 17, IL-23, and C-X-C motif chemokine ligand 13 (CXCL13)." (PMID 37175254, 2023). "Notably, increased CXCL13 expression was not seen in the healthy control, atopic dermatitis, or psoriasis controls." (PMID 40941016, 2025).
viral infection (23 papers, 2010 to 2025). "CXCL13 levels were significantly associated with antibody concentration and with the frequency of GC Tfh cells in both 17D yellow fever and HIV-1 vaccine recipients." (PMID 33732259, 2021). "Moreover, IRF7 deficient mice produced elevated levels of CXCL13 after virus infection and showed impaired regulation of microglia activity." (PMID 32046242, 2020). "Among these genes, XCL1 and CXCL13 are chemokines that inhibit the apoptosis of immune cells during viral infection and play an important part in inflammatory response and immune regulation." (PMID 39682511, 2024). "More importantly, AAV-hSyn-Cxcl13-injected group showed obvious mechanical allodynia starting from 4 weeks after viral infection." (PMID 37158939, 2023). "Recently, the level of CXCL13 in sera has been reported to be elevated in several viral infectious diseases, including severe acute respiratory syndrome coronavirus 2 (SARS-CoV-2), human immunodeficiency virus (HIV), and hepatitis B virus (HBV) infections." (PMID 37047294, 2023). "CXCL12 and CXCL13 are two well-documented B cell chemoattractants, and detection of CXCL12 and CXCL13 levels in BALF after viral infection revealed that CXCL13 expression at 3-5 d.p.i." (PMID 34868067, 2021). "For example, 17D yellow fever vaccine and HIV-1 vaccine both induce robust immune responses and were both associated with significant increases of plasma CXCL13 levels at 7 days post-vaccination in adults." (PMID 33732259, 2021). "It was important to note that both the elevated levels in sera and the increased expression in tissues of CXCL13 were associated with severe prognosis and increased mortality following these viral infections; therefore, CXCL13 has been proposed as a biomarker for predicting disease progression." (PMID 37047294, 2023). "Another viral infection of mice that mimics MS in which CXCL13 is upregulated is infection with mouse hepatitis virus (MHV), as shown in a study of wild-type and CXCL13-KO mice." (PMID 39766248, 2024). "Chemoattraction to follicles via direct secretion of CXCL13 by TFH cells or indirect promotion of CXCL13 secretion from mesenchymal cells by IL-17+ CD4+ T cells are known components of T cell help to B cells, including in the lung after viral infection." (PMID 38715601, 2024). "CXCL13, CCL19 and CCL21 have previously been shown to be essential components of the local airway immune response to viral infection and to be involved in iBALT formation, a recognised feature of long term pathogen exposure." (PMID 24847941, 2014). "The elevation of cytokine/chemokines in EVE is consistent with previously reported studies and the elevation of CXCL13, BAFF and APRIL highlight humoral mechanisms involved in protection against viral infections, possibly as a consequence of induction of these molecules by interferons." (PMID 27575749, 2016). "Whether Tph-like CD4+ T cells that produce CXCL13 are a common feature of virus infections is not known." (PMID 40956619, 2025). "In a recent study of 26 patients with bacterial or viral infections of the CNS34, not including LNB, increased levels of CXCL13 in the CSF samples of patients with a complicated disease course were observed." (PMID 37322136, 2023). "Others have similarly failed to observe post-vaccination changes in CXCL13 concentration, and the original report, in fact, observed this only with HIV and yellow fever vaccines, but not with an inactivated trivalent influenza vaccine." (PMID 33763653, 2021).
encephalitis (22 papers, 2010 to 2025). An acute inflammatory process affecting the brain parenchyma. "A published review of CSF cytokines in children also found Th1 cytokines to be associated with viral encephalitis and CXCL13 and IL6 to be associated with NMDAR-antibody associated encephalitis and non-herpetic limbic encephalitis, respectively." (PMID 32116981, 2019). "Additionally, CXCL13 elevations in cerebrospinal fluid have been implicated in bacterial/viral and aseptic meningitis and encephalitis." (PMID 39636121, 2025). "The increased concentration of CSF CXCL13 in patients with anti-NMDAR encephalitis is associated with the synthesis of intrathecal anti-NMDAR antibodies, and thus, it may be a possible biomarker for evaluating the treatment response and prognosis." (PMID 35937071, 2022). "However, the subsequent clinical course of the disease was consistent with that of a severe case of anti-NMDAR encephalitis, the severity of which is usually associated with high antibody titers in CSF, increased intrathecal synthesis of GluN1 antibodies, or increased CSF CXCL13 concentration." (PMID 40130117, 2025). "Studies on encephalitis patients, including multifaceted diagnostics and especially a full CSF data report with novel biomarkers, e.g., C-X-C-motif chemokine ligand 13 (CXCL13), are scarce." (PMID 40868960, 2025). "The results suggest that the CXCL13 concentration increases with disease progression and development of complications (e.g., encephalitis)." (PMID 34638953, 2021). "Patients with early stage anti‐NMDAR (N‐methyl‐D‐aspartate receptor) encephalitis had an increased CSF CXCL13 concentration." (PMID 32314548, 2020). "The serum and CSF levels of C-X-C motif chemokine ligand 13 (CXCL13) were significantly higher in patients with LGI1 encephalitis." (PMID 33396564, 2020). "With this observational study, we provide the first evidence that CXCL13 elevations in CSF occur during progress of infections and signal possible complications, such as parenchymal involvement seen in encephalitis, myelitis, abscesses, and vasculitis." (PMID 30660201, 2019). "We observed that TNF-α, IL-10, IFN-α, IL-6, CXCL10 and CXCL13 demonstrated >79.1% sensitivity in patients with encephalitis using control 95th centile as cut off (specificity 95%)." (PMID 27575749, 2016). "The potential role of monoclonal antibodies against CXCL10, CXCL13 as therapeutic targets in encephalitis needs further investigation." (PMID 27575749, 2016). "Only CSF CXCL13 showed a positive correlation with CSF cell count in all encephalitis patients (r = 0.54, P = 0.0002)." (PMID 27575749, 2016). "Elevated CXCL13 in CSF, however, also occur in other inflammatory central nervous system (CNS) diseases such as bacterial and viral meningitis, encephalitis, myelitis, and CNS lymphoma and in patients with autoimmune CNS diseases such as multiple sclerosis (MS) and autoimmune encephalitis (AIE)." (PMID 30660201, 2019). "Given their association with worse outcome, certain key chemokines (CXCL13, CXCL10) could represent potential therapeutic targets in encephalitis." (PMID 27575749, 2016). "Furthermore, CSF CXCL13 was found to be elevated in other inflammatory CNS diseases including viral meningitis and encephalitis, confirming its role as a suitable marker of B cell recruitment." (PMID 20700489, 2010). "Notably, elevated CXCL13 levels in CSF are specific to anti-NMDAR encephalitis instead of anti-LGI1 encephalitis, which may be due to the different IgG subtypes between the two diseases." (PMID 35937071, 2022). "Some of these molecules (CXCL13 and CXCL10) may represent potential therapeutic targets in view of their association with severity of encephalopathy at admission and worse disability at follow up in all encephalitis cases." (PMID 27575749, 2016).
encephalitis (continued). "The alteration in the concentration of the different chemokines, such as CXCL10, CXCL-13, CCL-4, CCL-17, CCL-20, and cytokines, including IL-2, IL-4, IL-6, IL-9, IL-10, and IFN-γ have been observed in encephalitis patients." (PMID 36048783, 2022). "The results showed that the expressions of cIAP-1, MCSF, CXCL13, and NLRP3 were higher in the anti-NMDAR encephalitis group than controls and the viral encephalitis group (p < 0.05)." (PMID 36389787, 2022). "CASPR2 encephalitis seems to elicit a higher immune response than LGI1 encephalitis, with more intrathecal IgG and higher cytokine levels, indicated by higher CXCL13 and soluble intercellular adhesion molecule-1 (sICAM1) in the CSF." (PMID 33396564, 2020). "In descending order, CSF TNF-α, IL-10, IFN-α, IL-6, CXCL13 and CXCL10 had the best sensitivity (>79.1%) when all encephalitis patients were included." (PMID 27575749, 2016). "Th1 and B cell (CXCL13 and CXCL10) molecules clustered together in patients with severe encephalopathy at admission and worse disability at follow up in all encephalitis." (PMID 27575749, 2016). "Of 3 cases studied with encephalitis relapses, IFN-α was elevated all cases where as CXCL10 and CXCL13 were elevated only in two cases." (PMID 27575749, 2016). "In our cohort of encephalitis, the Th1 (CXCL10 & TNF-α), T reg (IL-10), B cell (CXCL13) related cytokine/chemokines, and cytokines with broad spectrum of activities including IL-6 and IFN-α, were elevated in more than 75% of the cases." (PMID 27575749, 2016). "Various inflammatory cytokines/chemokines, such as IL-6, IL-17A, CXCL13 in cerebrospinal fluid, and IL-2 in plasma, and miRNAs (like e.g., Let-7b) in plasma, have been shown to play important roles in the process of anti-NMDAR encephalitis." (PMID 40948637, 2025). "Several studies have shown that IL-6 is elevated in the CSF of patients with anti-NMDAR encephalitis but not in anti-LGI1 encephalitis, often accompanied by increased IL-17A and CXCL13, suggesting a subtype-specific pattern of Th17-driven inflammation." (PMID 41041342, 2025). "In addition, the serum/plasma levels of the TNF-α were increased in encephalitis patients, but serum/plasma concentration of the IL-6, IL-10, CXCL10, and CXCL13 remained unchanged." (PMID 36048783, 2022). "The patients with MOG antibody positive associated demyelination showed predominant elevation of B cell related cytokine/chemokines (CXCL13, APRIL, BAFF and CCL19) compared to MOG antibody negative demyelination group as well as other encephalitis groups (CXCL13 and CCL19)." (PMID 27575749, 2016).
hepatocellular carcinoma (21 papers, 2010 to 2025). A malignant tumor that arises from hepatocytes. "More recently, close proximity of intrahepatic CD8+ T cells to Tph-like CD4+ T cells that produced IL-21 and CXCL13 was associated with reversal of exhaustion after immune checkpoint inhibitor blockade in hepatocellular carcinoma." (PMID 40956619, 2025). "In hepatocellular carcinoma, elevated serum levels of CXCL13 are positively associated with large tumor size and the late stage of the cancer." (PMID 36612163, 2022). "The chemokine CXCL13, initially identified as chemoattractant for B cells, and its receptor drives hepatocellular carcinoma progression by activating the Wnt/B-catenin pathway." (PMID 35935577, 2022). "RNA-seq of single cell T cells sorted from hepatocellular carcinoma samples identified an easily distinguished CXCL13+ CD4+ T cell population isolated from tumor tissue." (PMID 30190721, 2018). "Similarly, in hepatocellular carcinoma, elevated CXCL13 expression suggests a potential promotion of cancer growth via the Wnt/ß‐catenin pathway." (PMID 39344390, 2024). "Whether the CXCL13+ cells seen by RNA-seq and IL-21+ T cells detected by flow cytometry represent the same T cell population in hepatocellular carcinoma will be of interest to resolve." (PMID 30190721, 2018). "CXCL13 has been reported to be increased in the serum of patients with hepatocellular carcinoma (HCC)." (PMID 34947813, 2021). "Similar roles for CXCL9, CXCL13 and CXCL16 in T- and B-cell recruitment have been suggested in other models of liver disease including chronic Hepatitis C, Hepatocellular Carcinoma, Primary Biliary Cirrhosis and Primary Sclerosing Choliangitis." (PMID 20161726, 2010). "Elevated CXCL13 and CXCR5 expression has also been described in hepatocellular carcinoma (HCC) and was suggested to promote cancer growth through the Wnt/ß-catenin pathway." (PMID 36077611, 2022).
Sjögren’s syndrome (20 papers, 2008 to 2026). "Furthermore, multicolor flow cytometry revealed CXCL13+ Tph cells infiltrating Sjögren’s syndrome–associated (SjS-associated) organs, such as salivary glands." (PMID 41277554, 2025). "Recent studies suggest that elevated CXCL13 serum levels in patients with primary Sjögren’s syndrome (pSS) associate with minor salivary gland (MSG) histologic features, disease severity, as well as high-risk status for non-Hodgkin lymphoma (NHL) development and NHL itself." (PMID 34484201, 2021). "In this regard, antibody-mediated neutralization of CXCL13 in a mouse model for Sjögren’s syndrome resulted in improved disease phenotype and reduced lymphoid follicles in the submandibular glands." (PMID 27656182, 2016). "Although it is known that immunoreactive CXCL13 is present in salivary glands of patients with Sjögren's syndrome, to our knowledge the amount of CXCL13 in the sera of patients has not yet been reported." (PMID 22044682, 2011). "The chemokine CXCL13 was measured by ELISA in sera from Sjögren's syndrome patients (n = 27) and healthy controls (n = 30)." (PMID 22044682, 2011). "Pro-inflammatory cytokines IL-1β, IL-6, IL-17 and TNF-α, as well as chemokines CXCL8, CXCL10, and CXCL13 are significantly elevated in the saliva of patients with Sjögren’s syndrome compared to healthy controls, and that their levels are correlated with the activity and severity of disease." (PMID 38714918, 2024). "CXCL13 is also described to be a biomarker of histological involvement in Sjögren’s syndrome." (PMID 35309354, 2022). "In addition, CXCL13 strongly correlates with local pathology in Sjögren’s syndrome patients and elevated IL-10 levels in plasma and saliva correlate with disease severity and autoantibody titres." (PMID 34839819, 2021). "Additionally, there were two false positive cases of GBM and brain involvement of Sjögren's syndrome in the 4‐marker (CXCL13, IL‐10, β2‐MG, and sIL‐2R) and 3‐marker (CXCL13, IL‐10, and β2‐MG) algorithms." (PMID 32314548, 2020). "Serum CXCL13 concentrations were quantified by ELISA in 48 healthy individuals, 273 pSS patients without NHL (pSS-nonL), and 38 pSS patients with NHL (pSS-NHL+) from the United Kingdom Primary Sjögren’s Syndrome Registry cohort." (PMID 32047959, 2020). "In addition, CXCL13 production may be mediated by IL-1 in mice infected with IAV, by IL-22 in a mouse model of Sjögren’s syndrome and by TNF-α in the fat." (PMID 37047294, 2023).